NPR1 (natriuretic peptide receptor 1)
Diseases named in the same sentence as NPR1 in open-access papers (continued):
Sharing a sentence is not in itself a finding about the gene and the disease.
infection (continued). "SA- and JA/ET-dependent ISR induced by B. cereus AR156 required NPR1 after Pst DC3000 infection." (PMID 32899695, 2020). "Besides these post-translational mechanisms intensively studied in A. thaliana, regulation of NPR1 at the transcriptional level has also been observed in tomato and pepper during infection by B. cinerea." (PMID 33324431, 2020). "In Arabidopsis, the NPR1 transcripts accumulate constitutively at a low basal level throughout the plant, and the accumulation level can be induced two- to threefold upon pathogen infection or SA treatment." (PMID 33072146, 2020). "In B. subtilis PTA-271-treated plants, NPR1 might play a role as a mediator of SA-JA crosstalk, resulting in priming both SA- and ET/JA-responsive genes following infection with B. cinerea." (PMID 32899695, 2020). "However, npr1‐1 plants retained the ability to reduce SD following infection, suggesting that the systemic SD response is mediated by NPR1‐independent SA signalling." (PMID 31042812, 2019). "NPR1 oligomers become monomers under pathogen infection, and this process triggers SA accumulation." (PMID 30857376, 2019). "Under unchallenged conditions, NPR1 is present in the cytosol as a stable oligomer; however, upon pathogen infection, monomeric forms of NPR1 are transferred to the nucleus to bind the TGA family of transcription factors, activating the expression of defense-related genes, such as PR1 and WRKY." (PMID 29659986, 2018). "The LHT1 gene was upregulated by pathogen infection in wild type but not in a NahG transformant and SA pathway–deficient mutants such as pad4, sid2 and npr1." (PMID 26940322, 2016). "Resistance against the infection of P. sojae in soybean, P. capsici in Arabidopsis, and T. cacao was reported to be mediated by the salicylic acid signaling in which NPR1 was the key component." (PMID 27313593, 2016). "Taken together, these data implicate ethylene and an NPR1-independent function for SA in protecting the host against Agrobacterium, likely in part by attenuating the bacterial virulence machinery at early stages of the infection process." (PMID 25873923, 2015). "Once SA increases upon pathogen infection, NPR1 is stabilized." (PMID 25538725, 2014). "Our data have shown that expressing DN-AtRop1 led to decreased Npr1 transcript levels after infection with P. infestans, indicating that AtRop1 may positively regulated the NPR1 expression in potato." (PMID 25547733, 2014). "The 35S::AtELP3 transgene complemented all the phenotypes caused by the gns2 mutation in gns2 npr1, including partially restored SA tolerance, light green coloration, reduced SA accumulation after Psm ES4326 infection, and enhanced susceptibility to Psm ES4326." (PMID 23856002, 2013). "After pathogen infection, npr1 plants accumulate significantly higher levels of SA." (PMID 23856002, 2013). "Similarly to the previously characterized gns1 npr1, the gns2 npr1 mutant not only exhibited partially restored SA tolerance, but also accumulated significantly less SA than npr1 after infection by the virulent bacterial pathogen Pseudomonas syringae pv." (PMID 23856002, 2013). "This shows that plants impaired in SA signalling are unable to induce proteasome activity upon infection and opens the possibility that activation of the proteasome by SA could be mediated through NPR1." (PMID 23785289, 2013). "However, VIGS of NPR1 expression in pepper abrogates early tissue necrosis upon infection with Xcv ΔxopJ demonstrating the necessity of a functional SA signalling pathway for this type of host cell death to occur." (PMID 23785289, 2013). "npr1 mutants show enhanced susceptibility to both virulent and avirulent strains of Pst and accumulate very low levels of PR-1 and BGL2 transcripts in response to infection or SA-treatment." (PMID 23071821, 2012).
infection (continued). "NPR1 is a key regulator of the SA-dependent defence response and systemic acquired resistance (SAR), and plants under-expressing NPR gene are more susceptible to infection with pathogens." (PMID 22883108, 2012). "NPR1 is a key regulator of host responses to infection by biotrophic pathogens." (PMID 23071821, 2012). "After pathogen infection and in response to salicylic acid (SA) accumulation, NPR1 translocates from the cytoplasm into the nucleus where it interacts with other transcription factors resulting in increased expression of over 2000 plant defense genes contributing to a pathogen resistance response." (PMID 21078185, 2010). "In addition, UDP-GLUCOSYL TRANSFERASE 73B3 (UGT73B3) and UGT73B5 are directly activated by NPR1, and their protein products detoxify secondary metabolites accumulated after infection by bacteria harboring AvrRpm1 and consequently modulate redox-sensitive signaling pathways." (PMID 38261978, 2024). "Thus, it is likely that the differences in P. cinnamomi sensitivity between R0.12 and Dusa® may be dependent on variations in the regulation of the NPR1 pathway during the early stages of infection." (PMID 37936068, 2023). "However, during pathogen infection, redox changes occur in the cytoplasm which trigger the reduction of disulfide bonds, and monomeric NPR1 translocates into the nucleus, where it serves as a transcriptional co-activator at the target gene promoter, thereby activating defense gene expression." (PMID 38068630, 2023). "The reduced immunity in ald1npr1 and ald1sid2 mutants after avirulent P. syringae carrying AvrRpt2 infection could be due to the weakened SA-related defense as well as basal defense response resulting from the simultaneous mutation of ALD1 and NPR1 or ICS1/SID2." (PMID 36523630, 2022). "Genetic experiment revealed that NPR1 transcriptionally upregulates EDS1 expression via TGA2-NPR1 interaction, and in planta analysis discovered that EDS1 stabilizes NPR1 protein level by preventing its degradation to sustain immune responses under pathogenic infection." (PMID 35154230, 2022). "Moreover, high expression of NPR3 in atg4a4b may accelerate the degradation of NPR1 during AvrRpt2 infection." (PMID 32708160, 2020). "NPR1 genes are the central coregulator of defense-related gene activation in SA-signaling pathway and Fe acquisition and homeostasis could induce a burst of ROS during pathogen infection in plants." (PMID 33287151, 2020). "Upon pathogen infection, NPR1 oligomers in the cytosol are reduced into monomers and then NPR1 monomers enter the nucleus and interact with TGA and TCP transcription factor to activate the expression of PR genes, which encode small proteins that may have antimicrobial properties." (PMID 31288496, 2019). "Collectively, GhBOP1in disease resistance is a similar manner to that of NPR1, and in response to pathogen infection, may accumulate in the nucleus and/or become activated so that they may complex with TGA3 to promote the transcription of defence-related genes." (PMID 31263782, 2019). "Thus, in response to the PM infection, the NPR1, PAL (except at 24 and 48 h), and PDF1.2 (except at 48 h) expression levels were significantly lower in the transgenic plants than in the WT plants, whereas the opposite pattern was observed for the PR1a, and PR5 expression levels." (PMID 31402923, 2019). "Moreover, PR1 could be further induced in the npr1 mutant by the infection of different accessions of Botrytis cinerea indicating other unknown signals bypassing NPR1." (PMID 30544557, 2018). "Delayed lesion growth in vtc2 plants at early infection stages is likely due to defense priming caused in part by the activation and nuclear localization of redox sensitive Nonexpressor of PR Genes 1 (NPR1), which transcriptionally activates PR1 and other defense regulators." (PMID 29036633, 2017). "The high levels of SA produced at the infection site could enhance basal resistance through NPR1." (PMID 27513560, 2016).
infection (continued). "Further results showed that silencing ATG6 in NPR1-GFP exacerbates Pst DC3000/avrRps4 infection, while double overexpression of ATG6 and NPR1 synergistically inhibits Pst DC3000/avrRps4 infection." (PMID 40036061, 2025). "In this study, the expression of genes related to NPR1, TGA, and PR1 was significantly higher in the disease spot tissues during the early and middle stages of infection compared to the late stage." (PMID 40094748, 2025). "Systemic signalling appears to prime leaves for enhanced immunity, as evidenced by sustained NPR1 induction and subsequent activation of POD following infection." (PMID 40508296, 2025). "Treatment with SA or pathogen infection suppresses JA-regulated VSP2 expression in Arabidopsis, which also requires NPR1." (PMID 38780624, 2024). "We found that TuMV-GFP infection induced the expression of PR1 in both Col-0 and npr1 mutants compared with mock-infected plants at 2 dpi." (PMID 37328517, 2023). "In tissues distal to the initial site of infection where SA concentration is lower, SRK2C phosphorylates NPR1 precipitating its’ nuclear import during the onset of SAR." (PMID 37936068, 2023). "In addition, Fusarium oxysporum-infected cucumber shows strongly enhanced expression of PR3, LOX1, and NPR1, and it was recently reported that phenolic compounds and flavonoid-related metabolites accumulate in the cucumber PM-resistant cultivar BK following infection with S. fuliginea." (PMID 38003030, 2023). "This is because, under pathogen infection, SA level increases, which inhibits the CUL3NPR4 but promotes CUL3NPR3-mediated degradation of NPR1, leading to ETI." (PMID 35154230, 2022). "As the SA level increases after pathogen infection during basal resistance, SA binds to NPR4 and releases more NPR1, which activates the SAR." (PMID 35401694, 2022). "In contrast, after an infection that leads to strong pathogen recognition via the cytoplasmic immune receptor RPS2, ALD1 acts additively with both NPR1 and ICS1/SID2 to suppress pathogen growth." (PMID 36523630, 2022). "During pathogen infection, SA increases and binds to NPR3/NPR4, which releases the transcriptional repression of defense genes, allowing SA to bind NPR1, which in turn, activates the transcription of defense genes." (PMID 34979915, 2022). "Tomato DC3000 infection through both quercetin-mediated H2O2 generation and the involvement of SA and NPR1." (PMID 35910661, 2022). "We addressed this gap in knowledge and found that there are different requirements for ALD1, NPR1 and ICS1/SID2, depending on the P. syringae strain used for infection." (PMID 36523630, 2022). "NPR1 degradation is important for the full range of defence gene activation and for activation of ETI and programmed cell death at the infection site, where SA levels are high, whereas in neighbouring cells SA levels are intermediate to allow NPR1 function." (PMID 34439788, 2021). "After mock infection, ICS1 transcript levels in fitness-1/npr1 mutants were similar to those measured in npr1 mutants and lower than those measured in fitness mutants, reinforcing the idea that FITNESS modulates SA synthesis." (PMID 33613599, 2021). "The expression of WRKY TFs at early time points after infection directly influenced the induction of SA related signaling genes PAD4, NPR1, ICS1, EDS1, and PR1 in the C6 CAGC treatment with response to Xoo." (PMID 34630495, 2021). "The expression of WRKY TFs at early time points after infection triggers SA related signaling genes PAD4, NPR1, ICS1, EDS1, and PR1 in the C6 CAGC treatment with response to Xoo." (PMID 34630495, 2021). "After infection with Pst DC3000, KO2 and npr1-1 plants were the only lines showing a significantly higher efficiency of photosystem II than wild-type infected plants." (PMID 34394146, 2021). "Consistent with the pattern seen for NPR1, TGA1 was also induced by KPF during the early stage of infection." (PMID 35082814, 2021).
infection (continued). "The expression levels of RIN4, RPM1, RPS2, NPR1, and TGA were significantly up-regulated at all infection stages." (PMID 34630478, 2021). "Upon pathogen infection or SA treatment, the N-terminal BTB/POZ domain of NPR1 interacts with TGA2, masking its repressor domain and forming an enhancesome with TGA2 to activate PR1 transcription." (PMID 32865553, 2020). "It is well known that pathogen infection induces biosynthesis of SA and expression of SAR-regulating genes including NPR1." (PMID 33072146, 2020). "The expression of NPR1, NPR3 and NPR4 in WT and atg4a4b increased, and then declined gradually with AvrRpt2 infection time at the initial stage of infection." (PMID 32708160, 2020). "First, we checked the autophagic vesicle formation directly in the GFP-ATG8a and npr1 (GFP- ATG8a) with concanamycin A (ConA) and wortmannin (WM) by confocal microscopy under AvrRpt2 infection." (PMID 32708160, 2020). "Meanwhile, GSO2 sense the infection of P. litchii and enhance resistance by up-regulated SDR1, which in turn induce resistance by up-regulated RFOs related genes, NPR1, and PP2Cs at 24 hpi." (PMID 30808947, 2019). "A high SA concentration at the infection site binds NPR3, thus promoting NPR1 degradation, leading to plant cell death at the infection site and hindering the spread of pathogen infection." (PMID 31653915, 2019). "More specifically, we found that differences in the plant susceptibility to the Pst-DC3000 infection depend on whether the NPR1 protein is functionally active or not with about 99% of variability in Pseudomonas spore growth between npr1 mutant and Wt plant samples." (PMID 29169324, 2017). "We applied the protocol to the phenotype dataset expressed in terms of leaf spore counts of 60 npr1 gene mutant and wild-type Arabidopsis thaliana plants following Pst-DC3000 infection." (PMID 29169324, 2017). "In the case of WRKY70, NPR1, and PR1, maximum relative expressions were detected at the latest stage of the infection (8 dai), when the highest viral loads were reached." (PMID 27933078, 2016). "SA signaling through NPR1 is required to establish systemic acquired resistance (SAR), an inducible broad-spectrum defense mechanism against secondary infection." (PMID 27513560, 2016). "These and other data led these authors to propose a model in which basal levels of NPR1 are modulated upon ETI by the gradient of SA that develops in and around the site of infection." (PMID 25873923, 2015). "NPR1 regulates nearly all of the BTH-responsive genes in Arabidopsis, except during early phases of pathogen infection." (PMID 25431577, 2014). "Infection of GhWRKY15 transgenic plants with TMV and C. gossypii increased the expression of NPR1, which is a key regulator of the SA-dependent defence pathway and SAR." (PMID 22883108, 2012). "In GmNPR1-1 and GmNPR1-2 transformed npr1-1 plants (i) SAR markers PR1 and BGL2 are induced following INA treatment and infection, respectively and (ii) SAR following infection." (PMID 19656407, 2009). "Both GmNPR1 proteins complemented the lost NPR1 function of the Arabidopsis npr1-1 mutant and mediated the expression of PR-1 and BGL2 following INA treatment and infection, respectively." (PMID 19656407, 2009). "Furthermore, qRT-PCR analysis revealed that, upon pathogen infection, the expression of pathogenesis-related genes such as PR1a, PR5, and NPR1 was significantly suppressed in the KO lines." (PMID 40650151, 2025). "For example, NPR1 (CCA0526S0239) and XLOC_017500 were predominantly expressed during the middle and late infection stages, whereas genes such as the chitin recognition protein gene (CCA0762S0079) and another NPR1 (CCA0526S0240) were more highly expressed in the early and middle stages." (PMID 40094748, 2025).
infection (continued). "In Arabidopsis, SA biosynthesis was mediated through the AtHDA19 gene, and plants with overexpression of AtHDA19 (NPR1, SID2, and NAHG) exhibited elevated SA levels and significantly increased expression of SA biosynthesis genes both before and after infection with Pseudomonas syringae pv." (PMID 40687930, 2025). "We also discovered that UGT76B1 impacts on a group of genes showing non-SA-responsiveness and regulation by infections independent from SID2/NPR1." (PMID 38780624, 2024). "Besides FMO1, 70 further, ugt76b1-upregulated genes can be induced by pathogen infections independent from SID2 and NPR1." (PMID 38780624, 2024). "This study found that proteins such as NPR1, TGA and PR1 in plant hormone signal transduction pathway were up-regulated after infection, which may activate a series of plant secondary metabolic synthesis pathways." (PMID 39574453, 2024). "Moreover, many genes among the SA-responsive group can be regulated by pathogen infections independent from both SID2 and NPR1, suggesting the existence of an independent signaling pathway that can target the same genes as SA." (PMID 38780624, 2024). "In the absence of pathogen infection, NPR1 oligomerizes in the cytoplasm through intermolecular disulfide bonds." (PMID 38068630, 2023). "In the absence of pathogen infection, NPR1 disappears from the nucleus via the 26 S proteasome pathway." (PMID 37230965, 2023). "We propose that the non-expressor of PR Gene 1 (NPR1), a protein that protects plants during pathogen infections, also responds to SA during drought to sustain ROS levels and prevent ROS-induced cell death." (PMID 37765358, 2023). "Recent research has demonstrated that autophagy modulates NPR1-dependent salicylic acid signaling via a negative feedback loop, which is required to limit excessive senescence in response to pathogen infection." (PMID 38132756, 2023). "On the other hand, ‘SMK’ plants showed almost no regulation in SA genes in response to G5H infection except for a temporary decrease in the expression of NPR1 at 1 dpi." (PMID 37099452, 2023). "We do not have any direct evidence to explain the inability of npr1- and sid2-exudates collected after infection to confer immunity, but one possibility is that the npr1 and sid2 mutants can not produce enough signal molecule(s)." (PMID 36523630, 2022). "To understand the roles of ALD1, NPR1, and ICS1/SID2 in the immune response during infection with PsmES4326/AvrRpt2 in detail, we examined the strength of SA-related defenses in WT and mutants after infection." (PMID 36523630, 2022). "However, in ACC-treated YZ1 root tissues, NPR1, PR1 and PR5 expression was significantly increased after Vd991 infection for 72 h." (PMID 35918649, 2022). "Upon pathogen infections, elevated level of SA promotes massive transcriptional reprogramming in which Non-expresser of PR genes 1 (NPR1) acts as a central hub and transcriptional coactivator in defense responses." (PMID 35154230, 2022). "In most infections that we studied, each defense module relying on ALD1, NPR1 or ICS1/SID2 can be sufficient to inhibit attenuated or virulent P. syringae growth; an additive effect between ALD1 and NPR1 or ICS1/SID2 is not detectable during these Arabidopsis-P." (PMID 36523630, 2022). "As a transcription inhibitor, NPR3/NPR4 inhibits the response of the SA pathway in the absence of pathogen infection, which is the opposite function of NPR1 in plant immune regulation." (PMID 36555841, 2022). "Many DEGs related to SA (regulatory protein NPR1), ET (8 ethylene-responsive TF and 4 ET-insensitive protein 3), and JA (four ZIM domain-containing proteins) biosynthesis and signal transduction were activated after the Fpmd MR5 infection of apple roots." (PMID 35780085, 2022). "The reduced dual phosphorylation of MPK3 and MPK6 in single and double mutants 30 min after inoculation prompted us to test whether ALD1, NPR1, and ICS1/SID2 control basal defense responses to PstDC3000 ΔAvrPto/ΔAvrPtoB infection." (PMID 36523630, 2022).